LAPTM5 (lysosomal protein transmembrane 5)
Description:
May have a special functional role during embryogenesis and in adult hematopoietic cells.
Synonyms: CLAST6
Tractability: Antibody: its Gene Ontology location is reachable by antibodies, with high confidence; UniProt predicts a signal peptide or a membrane-spanning region. PROTAC: ubiquitination databases record sites on it.
Gene: Protein-coding gene on chromosome 1 (30,732,465 to 30,757,855, reverse strand). Ensembl gene ENSG00000162511.
Subcellular location: Lysosome membrane
Subcellular location (Human Protein Atlas): Cytosol
Gene Ontology:
Molecular function: protein binding; ubiquitin protein ligase binding; protein sequestering activity; enzyme binding
Biological process: defense response to tumor cell; induction of programmed cell death; intrinsic apoptotic signaling pathway; negative regulation of autophagic cell death; positive regulation of lysosomal membrane permeability; Golgi to lysosome transport; intracellular protein transport; negative regulation of B cell activation; negative regulation of interleukin-2 production; negative regulation of T cell activation; negative regulation of T cell receptor signaling pathway; negative regulation of type II interferon production; positive regulation of cytokine production involved in immune response; positive regulation of interleukin-12 production; positive regulation of macrophage cytokine production; positive regulation of MAPK cascade; positive regulation of non-canonical NF-kappaB signal transduction; positive regulation of protein ubiquitination; positive regulation of receptor catabolic process; positive regulation of tumor necrosis factor-mediated signaling pathway; positive regulation of ubiquitin-dependent protein catabolic process; protein targeting to lysosome; regulation of lysosomal membrane permeability; negative regulation of activated T cell proliferation; negative regulation of pre-B cell receptor expression; and 2 more
Cellular component: cytoplasmic vesicle; lysosomal membrane; lysosome; perinuclear region of cytoplasm; plasma membrane; protein-containing complex; transport vesicle; cytosol; membrane
Genetic constraint (gnomAD): Loss-of-function variants: 10 observed, 21.88 expected, observed/expected ratio (o/e) 0.46, 90% interval 0.28 to 0.77. The upper end of that interval is the gene's LOEUF score, 0.77, which puts it in group 3 of 6, group 1 being the genes least tolerant of losing a copy. Missense variants: 276 observed, 280.32 expected, observed/expected ratio (o/e) 0.98, 90% interval 0.89 to 1.09. Synonymous variants: 136 observed, 118.84 expected, observed/expected ratio (o/e) 1.14, 90% interval 1 to 1.32.
Homologues: Orthologues: chimpanzee LAPTM5 (99% identical), macaque LAPTM5 (95% identical), pig LAPTM5 (86% identical), guinea pig LAPTM5 (80% identical), mouse Laptm5 (79% identical), dog LAPTM5 (78% identical), rat Laptm5 (73% identical), Drosophila melanogaster CG14767 (20% identical). Paralogues in human: LAPTM4B (23% identical), LAPTM4A (21% identical).
Diseases named in the same sentence as LAPTM5 in open-access papers:
LAPTM5 is named in the same sentence as 73 diseases in open-access papers, as found by Europe PMC text mining. Sharing a sentence is not in itself a finding about the gene and the disease. The quoted sentences say what the papers report.
neuroblastoma (10 papers, 2009 to 2024). Neuroblastoma (NB) is the most common solid, extracranial childhood tumor. "The LAPTM5 gene encodes for a lysosomal-associated multispanning membrane protein that is known to be associated with spontaneous regression of neuroblastomas, pigmented villonodular synovitis, and lung cancer." (PMID 26297037, 2015). "LAPTM5 is also associated with the spontaneous regression of neuroblastoma." (PMID 33976979, 2021). "However, a recent report suggested that LAPTM5 is downregulated in human cancers, such as neuroblastoma, and that low levels of LAPTM5 are associated with poor prognosis." (PMID 31701625, 2020). "Interestingly, the accumulation of LAPTM5-positive vesicles is associated with programmed cell death occurring during the spontaneous regression of neuroblastomas." (PMID 28464033, 2017). "Furthermore, it remains obscure whether the cell death caused by the LAPTM5 accumulation in neuroblastoma cells can be extended to cervical cancer HeLa cells." (PMID 28464033, 2017). "LAPTM5 expression is generally downregulated in neuroblastoma cells due to cell-specific DNA methylation, but is upregulated in degenerated neuroblastoma cells in locally degenerated tumors regions, as detected by large-scale screening." (PMID 39281638, 2024). "The therapeutic potential of LAPTM5 appears significant and warrants further in-depth investigations to validate its role as a therapeutic target in neuroblastoma." (PMID 39281638, 2024). "Overexpression of ITCH leads to the degradation of the LAPTM5 protein, while inhibition of ITCH enhances LAPTM5 accumulation in neuroblastoma cells, leading to increased cell death." (PMID 39281638, 2024). "It has been previously demonstrated that LAPTM5 expression level is decreased in neuroblastoma (NB) cells, and excessive accumulation of LAPTM5 was shown to induce lysosomal cell death in these cells." (PMID 27058622, 2016). "The cell death induced in neuroblastoma cells after Adenovirus-LAPTM5 (Ad-LAPTM5) infection is not blocked by the pan-caspase inhibitor z-VAD-fmk, but is enhanced in the presence of both proteasomal and lysosomal inhibitors, causing the accumulation of LAPTM5-positive vesicles." (PMID 28464033, 2017). "It has also been reported that the accumulation of LAPTM5 protein in Ad-LAPTM5-infected neuroblastoma cells induces caspase-independent non-apoptotic cell death with lysosomal destabilization and LMP, which allows lysosomal cathepsin D release into the cytosol." (PMID 28464033, 2017).
bladder cancer (8 papers, 2021 to 2023). "However, in a bladder cancer study, LAPTM5 deficiency suppressed cell proliferation and activity." (PMID 36046710, 2022). "It has been shown that inhibition of LAPTM5 blocks bladder cancer cell proliferation and cell cycle via deactivation of ERK1/2 and p38 and that silencing of STK32C inhibited tumor cell proliferation, migration, and invasion in human bladder cancer cells." (PMID 36139698, 2022). "LAPTM5 is a positive regulator of the inflammatory signaling cascade in macrophages, and low expression of LAPTM5 inhibits the bladder cancer cell cycle." (PMID 35711523, 2022). "Its relevance for tumor cell invasion was initially investigated in bladder cancer cells and a positive effect of LAPTM5 on proliferation as well as migration and invasion was revealed." (PMID 34116687, 2021). "It is reported that LAPTM5 can regulate the proliferation and viability of bladder cancer cells, leading to cell cycle arrest in the G0/G1 phase." (PMID 33976979, 2021). "In bladder cancer, LAPTM5 knockdown inhibited cell proliferation and the cell cycle." (PMID 36385959, 2022).
glioma (8 papers, 2020 to 2026). A benign or malignant brain and spinal cord tumor that arises from glial cells (astrocytes, oligodendrocytes, ependymal cells). "One of related studies showed that high protein levels of LAPTM5 were associated with a poor survival rate in glioma patients." (PMID 39281638, 2024). "As CD40 is known to be involved in several immune effects, we excluded that the observed association of CD40 high-expressing and LAPTM5 high-expressing gliomas with better prognosis is related to differences in the signature of immune cells." (PMID 32582531, 2020). "Preclinical data link LAPTM5 to stroke outcomes via stress-kinase and lysosomal pathways, while LAPTM4A and LAPTM4B associate with glioma progression, immune evasion, and therapy resistance." (PMID 41666016, 2026). "Conversely, an in vivo study screening genes involved in glioma invasion identified LAPTM5 as a highly anti-invasive gene for glioblastoma." (PMID 39281638, 2024). "Based on patient survival data and functional in vitro and in vivo experiments, we concluded that LAPTM5 acts as a tumor suppressor in CD40-positive gliomas." (PMID 32582531, 2020). "In that manner, LAPTM5 might be a mechanism used by gliomas to negatively modulate the antitumoral response of the immune system." (PMID 31701625, 2020). "LAPTM5 knockdown resulted in CD40-mediated NF-B activation, which enhanced invasion, clonality, and temozolomide resistance in glioma." (PMID 39281638, 2024). "Specifically, LAPTM5 exhibits tumor suppression and sensitivity to temozolomide by inhibiting the CD40-mediated NF-kB activation in CD40-positive gliomas." (PMID 39281638, 2024). "The aim of this study was to decipher the function of LAPTM5 in glioblastoma and its interaction with the CD40 receptor which is intensively evaluated as a target in the therapy of diverse cancers including glioma." (PMID 32582531, 2020). "LAPTM5 and CD40 were correlated with the clinical outcome of glioma patients." (PMID 32582531, 2020). "In addition, LAPTM5 inhibits tumor invasion, clonogenicity, and tumorigenicity by inhibiting NF-κB activation, which may act as a therapeutic target for CD40+gliomas." (PMID 36385959, 2022).
lung carcinoma (8 papers, 2013 to 2024). "The gene expression profiles and DNA methylation profiles illustrated that LAPTM5 is abnormally methylated in lung cancer, with its methylation status correlated with the tumor differentiation status." (PMID 39281638, 2024). "LAPTM5 knockdown leads to apoptosis in lung cancer cells; thus, inhibiting LAPTM5 expression has potential for the treatment of cancer." (PMID 36385959, 2022). "LAPTM5 can also be a biomarker in lung cancer, which shows a correlation between methylation and genes." (PMID 33521125, 2021). "As known, lung cancer poses significant public health challenges due to its high morbidity and mortality rates, which has also shown abnormal methylation and expression profiles of LAPTM5." (PMID 39281638, 2024). "Enrichment analysis confirmed that genes highly associated with B cells or DC1 strongly correlated with immune activation in lung cancer patients, with LAPTM5 being highly related to DC1, suggesting its role in predicting the efficacy of immune checkpoint blockade (ICB)." (PMID 39281638, 2024). "Additionally, we also showed that low expression of LAPTM5 was significantly correlated with poor prognosis in NSCLC patients by analysis of lung cancer gene expression datasets that included survival information (P = 0.043)." (PMID 27058622, 2016). "There is a lot of data showing that LAPTM5 and PTPRC are not only co-expressed in AD/PD, but also in systemic lupus erythematosus, lung cancer, and other diseases." (PMID 35912089, 2022). "To facilitate clinical application, in the lung cancer transcriptome, including 19,464 protein-coding genes, we extracted the three most relevant genes of B cell (CD19, TLR10, and FCRLA) and DC1 (ITGB2, LAPTM5, and SLC7A7), respectively." (PMID 34422829, 2021). "MEOX2 was uniformly higher methylated in all lung cancer samples, while the methylation of the other three genes was correlated with either the differentiation status of the tumor (MDK, LAPTM5) or with the tumor histopathological type (FGFR3)." (PMID 23086271, 2013).
cardiac hypertrophy (4 papers, 2021 to 2025). "Our results may help to obtain a deeper understanding of the association between LAPTM5 and ROS as well as autophagy in the development of cardiac hypertrophy." (PMID 35157609, 2022). "Since LAPTM5 is essential in the process of digestion of ingested materials in phagocytes and the proteolytic activity of lysosomes, we speculated that LAPTM5 might be associated with autophagy required for ROS production and that it may augment the inflammatory response and cardiac hypertrophy." (PMID 35157609, 2022). "After 4 weeks of AB, LAPTM5 gene-deleted mice showed worsening pathological myocardial hypertrophy, as assessed by higher heart weight (HW)/body weight (BW), lung weight (LW)/BW and HW/tibial length (TL) than WT controls." (PMID 34692792, 2021). "Collectively, our results delineated that LAPTM5 ameliorates the development of pathological cardiac hypertrophy by interacting with Rac1 and then blocking the activation of the Rac1-dependent signaling cascade." (PMID 34692792, 2021). "When we knocked out LAPTM5 in mice, the pathological cardiac hypertrophy phenotype became even worse with larger LV mass, fibrosis and cardiac dysfunction." (PMID 34692792, 2021). "In the second step, we tried to clarify the regulatory effect of LAPTM5 on pathological cardiac hypertrophy." (PMID 34692792, 2021). "To clarify the role of LAPTM5 in pathological cardiac hypertrophy, we detected the expression level of LAPTM5 under various pathological stimuli." (PMID 34692792, 2021). "To further confirm the regulatory effect of LAPTM5 on cardiac hypertrophy in vivo, we generated LAPTM5 global knockout (KO) mice." (PMID 34692792, 2021). "At the molecular level, we identified that the beneficial effect of LAPTM5 on cardiac hypertrophy was largely dependent on the regulation of the Rac1-MEK-ERK1/2 signaling pathway." (PMID 34692792, 2021). "In this study, we investigated the role of LAPTM5 in pathological cardiac hypertrophy and its possible mechanism." (PMID 34692792, 2021). "Taken together, these results demonstrate that LAPTM5 ameliorates the development of pathological cardiac hypertrophy by interacting with Rac1 and then blocking the activation of the Rac1-dependent signaling cascade." (PMID 34692792, 2021). "In conclusion, our results suggest that LAPTM5 is involved in pathological cardiac hypertrophy and that targeting LAPTM5 has great therapeutic potential in the treatment of pathological cardiac hypertrophy." (PMID 34692792, 2021). "In this study, we provide evidence that LAPTM5 also plays an important role in cardiac hypertrophy via the Rac1-MEK-ERK1/2 pathway." (PMID 34692792, 2021). "In addition, the transcription of cardiac hypertrophy markers in LAPTM5-ko mice was significantly increased." (PMID 34692792, 2021). "In addition, cardiac LAPTM5 overexpression by AAV9 injection ameliorated pressure overload-induced cardiac hypertrophy." (PMID 34692792, 2021). "Additionally, we supported the protective role of LAPTM5 in cardiac hypertrophy using a LAPTM5-overexpressing AAV9 delivery system in vivo." (PMID 34692792, 2021). "Together, these data suggest that LAPTM5 protects against cardiac hypertrophy and heart failure." (PMID 34692792, 2021). "Our results show that LAPTM5 gene deletion significantly exacerbates cardiac remodeling, which can be demonstrated by reduced myocardial hypertrophy, fibrosis, ventricular dilation and preserved ejection function, whereas the opposite phenotype was observed in LAPTM5 overexpression mice." (PMID 34692792, 2021). "In addition, deletion of the LAPTM5 gene aggravated pressure load-induced myocardial hypertrophy and heart failure in mice." (PMID 34692792, 2021). "However, overexpression of LAPTM5 protein in the heart can reduce myocardial hypertrophy and cardiac dysfunction induced by chronic pressure overload." (PMID 34692792, 2021).
cardiac hypertrophy (continued). "Because the MAPK pathway plays a key role in pathological cardiac hypertrophy, we examined whether LAPTM5 affects these signaling molecules." (PMID 34692792, 2021). "Together, these results indicate that LAPTM5 may function as a positive regulator in cardiac hypertrophy." (PMID 34692792, 2021). "Our results further supported that LAPTM5 overexpression may attenuate the development of pathological cardiac hypertrophy by blocking the activation of MEK 1/2 and ERK1/2." (PMID 34692792, 2021). "Furthermore, LAPTM5 could play an important protective role in pathological myocardial hypertrophy through the Rac1-MEK-ERK1/2 pathway." (PMID 36046710, 2022). "Thus, we are interested in determining whether LAPTM5 can function as a regulator in cardiovascular diseases, especially the development of cardiac hypertrophy and heart failure." (PMID 34692792, 2021). "Mechanistically, LAPTM5 directly bound to Rac1 and further inhibited MEK-ERK1/2 signaling, which ultimately regulated the development of cardiac hypertrophy." (PMID 34692792, 2021). "Indeed, deletion of LAPTM5 was found to exacerbate pressure overload-induced cardiac hypertrophy and MAPK/ERK signaling while overexpression of LAPTM5 in the heart reduced cardiac hypertrophy and MAPK/ERK activation in response to pressure overload." (PMID 41333012, 2025).